NUPR1 (nuclear protein 1, transcriptional regulator)
Diseases named in the same sentence as NUPR1 in open-access papers (continued):
Sharing a sentence is not in itself a finding about the gene and the disease.
NUPR1 also shares sentences with these, for which no sentence is quoted: cholangiocarcinoma (4 papers); diabetes (3); oral squamous cell carcinoma (3); thyroid cancer (3); breast tumor (2); idiopathic pulmonary fibrosis (2); iron metabolic disorder (2); lung adenocarcinoma (2); rheumatoid arthritis (2); bacterial infections (1); bladder transitional cell carcinoma (1); brain tumors (1); breast invasive carcinoma (1); cardiac hypertrophy (1); cervical cancer (1); chronic hepatitis (1); Cirrhosis (1); Cognitive impairment (1); diabetic nephropathy (1); emphysema (1); erectile dysfunction (1); esophageal squamous cell carcinoma (1); gastric cancer (1); infectious disease (1); intrahepatic cholangiocarcinoma (1); invasive ductal carcinoma (1); kidney chromophobe (1); kidney disease (1); lepromatous leprosy (1); liver cirrhosis (1).
A further 16 diseases each share a sentence with NUPR1 in 1 paper.